TNF (tumor necrosis factor)
Diseases named in the same sentence as TNF in open-access papers (continued):
Sharing a sentence is not in itself a finding about the gene and the disease.
pulmonary fibrosis (continued). "Similarly, in the Han population of Southwest China, TNF gene polymorphisms (−308A/G and −238A/G) might be related to occurrence of silicosis and the degree of severe pulmonary fibrosis in silicosis." (PMID 30643011, 2019). "In addition, mice deficient in TNFα exhibited delayed resolution of bleomycin-induced pulmonary fibrosis, further showing that TNFα may be important in the resolution phase of fibrosis by inducing antifibrotic macrophages." (PMID 26618160, 2015). "With this aim in mind, authors carried out a second case-control study where TNF was studied as a potential risk factor and concluded that TNF release from peripheral blood monocytes exposed coal mine dust was a marker of individual susceptibility to dust-induced lung fibrosis." (PMID 16042760, 2005). "This suggests that the MMP9, IL-6, and TNF-α collectively exert multiple effects in driving lung fibrosis progression." (PMID 40630478, 2025). "A previous study reported that the fenugreek seed extract reduced IL-6 in an ovariectomized rat model and downregulated NF-κB, TNF-α, IL-6, IL-8, and IL-1β in a pulmonary fibrosis animal model." (PMID 39941027, 2025). "The core targets actively interact with major pathways in pulmonary fibrosis, including TNF, HIF-1, FOXO, AGE-RAGE, PD-L1 expression, VEGF, IL-17, relaxin, ErbB, and EGFR tyrosine kinase inhibitor resistance pathways." (PMID 41361355, 2025). "This has also been demonstrated in animal models, with motheaten mutant mice exhibiting rapid progression of pulmonary fibrosis due to elevated levels of TNF-α in both serum and lungs." (PMID 41155396, 2025). "Five studies evaluated the impact of Ginkgo biloba leaf extract on TNF-α levels in patients with pulmonary fibrosis, with two studies utilizing bronchoalveolar lavage fluid specimens and three employing blood samples." (PMID 40110130, 2025). "We found that the expression levels of p-NF-κB, IL1, IL6, and TNF-α were significantly upregulated in the pulmonary fibrosis model mice, while their expression was significantly inhibited after treatment with SGZ." (PMID 40731787, 2025). "Regulation of fibrotic foci formation through TNF/NF-κB and TGFβ1 signaling pathways by SC offers a new therapeutic approach for treating pulmonary fibrosis." (PMID 41361355, 2025). "Inhibition of lung injury healing, promotion of lung cell death, and eventual induction of pulmonary fibrosis can be caused by TGF-β1, IL-1β, IL-6, and TNF-α." (PMID 40665395, 2025). "In the early silicosis stages, MMP9 disrupts lung tissue and increases the infiltration of inflammatory cells and corresponding inflammatory mediators, such as TNF-α and other cytokines, to promote the development of pulmonary fibrosis." (PMID 40470053, 2025). "TNF-α promotes detrimental tissue damage and gradual lung fibrosis, which results in pneumonia, pulmonary edema, and acute respiratory distress syndrome." (PMID 40881695, 2025). "TNF-α (Tumor Necrosis Factor alpha): Serum levels of TNF-α are elevated in patients with SSc, particularly those with pulmonary fibrosis." (PMID 41155396, 2025). "Similar to IL-6, TNF-α contributes to lung fibrosis by promoting inflammation, oxidative stress, tissue remodeling, and fibroblast activation, and its levels are elevated in IPF patients and experimental models." (PMID 40630478, 2025). "Overexpression of TNF-α can lead to emphysema, pulmonary fibrosis, and muscle mass reduction in COPD patients." (PMID 40343927, 2025). "This study investigates the therapeutic mechanism in fibrotic foci reconfiguring via the TNF signaling pathway by potential Swertia chirayita (SC) components to treat pulmonary fibrosis by network pharmacology, in silico, and in vitro studies." (PMID 41361355, 2025). "Mangiferin (MANG) and gentiopicroside (GENPD) have been shown to have an anti-fibrotic effect in preclinical studies for treating pulmonary fibrosis by regulating inflammatory markers (TNF, IL-17, and IL-6) and TGFβ1/Smad and TNF-α/NF-κB signalings." (PMID 41361355, 2025).
pulmonary fibrosis (continued). "In mice treated with BLM, atRA attenuated the upregulation of IL-17A, IL-10, IL-6, EphA2, EphriA1, PI3K 110γ, Akt, IL-6, TNF-α, and TGFβ1, which reduced pulmonary fibrosis and significantly alleviated lung fibrosis." (PMID 40508111, 2025). "Research conducted by Ying-Wei Lan showed that, compared with mice with induced pulmonary fibrosis, the group treated with Kefir yogurt showed a notable downregulation of pro-inflammatory factors such as IL-4, IL-6, and TNF-α." (PMID 39683559, 2024). "Thalidomide’s potential in mitigating lung damage by reducing TNF-alpha and suppressing lung fibrosis pathways is noteworthy." (PMID 39064155, 2024). "MiRNA-21a-5p overexpression promoted lung fibrosis in bleomycin-induced SSc mice, inducing infiltration of cells expressing TNF-α, IL-1β, IL-6, or IL-17, along with STAT3 phosphorylated cells in the lesional skin." (PMID 38561750, 2024). "iPSCs also, can downregulate the pro-fibrotic growth factors IGF-1,2, and repress several inflammatory mediators during pulmonary fibrosis, including TNF-α, IL-1β, IL-6, inducible nitric oxide synthase (iNOS) and nitric oxide (NO), but also PGE2." (PMID 38886859, 2024). "SSc fibroblasts are refractory to the anti-fibrotic effect that TNF-α exerts on healthy cells and is involved in the proinflammatory profile observed in the lung fibrosis in a murine model of SSc with bleomycin." (PMID 39185406, 2024). "This inhibitor is used commercially in patients who develop idiopathic pulmonary fibrosis and acts on signaling pathways triggered by TNF-α and TGF-β, such as SMAD and MAPK signaling pathway proteins." (PMID 39000409, 2024). "In the acute lung injury model, NKS3 decreased lung fibrosis and inflammatory cytokines (IL-1β, IL-6 and TNF-α) and nitric oxide (NO) production in broncho-alveolar lavage fluid." (PMID 38598021, 2024). "Serum levels of TNF-α are elevated in patients with SSc and favour the development of pulmonary fibrosis and pulmonary arterial hypertension." (PMID 38388392, 2024). "On the other hand, nintedanib (a tyrosine kinase inhibitor) and pirfenidone (an inhibitor of TGF-β, PDGF, and TNF-α singling) are anti-fibrotic therapies for idiopathic pulmonary fibrosis that can decelerate fibrosis and scarring." (PMID 38111379, 2023). "IL-1β and TNF-α work synergistically to increase the number of myofibroblasts, thereby promoting pulmonary fibrosis progression." (PMID 37214554, 2023). "administered TNF as a therapeutic into the lungs of WT mice with pre-established pulmonary fibrosis driven by bleomycin." (PMID 37465675, 2023). "The transgenic mouse model was established for modeling pulmonary fibrosis by intratracheal delivered with adenovirus vector, followed by overexpressing of TGFα, TNF-α, TGF-β, IL-13 or IL-1β." (PMID 38007420, 2023). "Serum TNF-α concentrations are elevated and correlate with pulmonary fibrosis and decreased vital capacity in SSc patients." (PMID 37531393, 2023). "Anti-TNF-related lung autoimmune disorders are mainly represented by interstitial lung diseases (ILDs) and pulmonary fibrosis, the most severe manifestation." (PMID 37175894, 2023). "Significantly enriched KEGG pathways included the MAPK signaling pathway, insulin resistance, TNF signaling pathway, lung fibrosis, TGFβ receptor signaling, pre-NOTCH Transcription and Translation, signaling by NOTCH, canonical and noncanonical TGFβ signaling." (PMID 37175790, 2023). "T lymphocytes led to impaired lung function and lung fibrosis by inducing an increase in lung TNF production." (PMID 37118713, 2023). "Early translational studies with this cytokine demonstrated its critical role in experimental models of pulmonary fibrosis as TNFα was shown to modulate expression of TGFβ in various cells in the lungs." (PMID 37849737, 2023). "In contrast, case reports have described ILDs and pulmonary fibrosis as paradoxical side effects of anti-TNF-α agents." (PMID 37175894, 2023).
pulmonary fibrosis (continued). "It has been demonstrated that TNF-α stimulates human fibroblasts and promotes fibrocyte differentiation in the lungs of pulmonary fibrosis patients and in vitro models of fibrosis." (PMID 37854602, 2023). "GSEA showed that DEGs in the CIP associated myeloid cell subclusters were enriched in inflammation pathway such as IFN, IL2, IL6, TNF signaling, and lung fibrosis." (PMID 37653115, 2023). "Overproduction of inflammatory mediators and cytokines such as inflammasome complexes, IL‐6, IL‐1β, TNF‐α, and the like leads to lung fibrosis in affected patients." (PMID 37773712, 2023). "In a bleomycin-induced mouse model of pulmonary fibrosis, early work showed elevated TNF upon bleomycin instillation and blocking TNF prevented fibrotic disease progression, including collagen deposition." (PMID 37465675, 2023). "On the other hand, systemic increase of activity of TNF-α and IL-1β, which are markers of M1 macrophages, has been shown to promote myofibroblast differentiation and exacerbate bleomycin-induced pulmonary fibrosis." (PMID 37291088, 2023). "Increasing evidence has shown that IL-1β, IL-6, and TNF-α contribute to the pathogenesis of pulmonary fibrosis." (PMID 36830999, 2023). "In later work also using the bleomycin model of pulmonary fibrosis, TNF-/- and TNFtm/tm (mice only expressing mTNF) mice were protected from pulmonary fibrosis as compared to WT controls." (PMID 37465675, 2023). "Consistent with the earlier studies, we found that overexpression of Sestrin2-inhibited ROS production and the level of TNF-α, IL-6, and IL-1β to attenuate endoplasmic reticulum stress and ferroptosis, thereby ameliorating lung fibrosis." (PMID 38023615, 2023). "In our 14-day BLM model of lung fibrosis, RP-832c also significantly decreased the mRNA expression levels of multiple cytokines, including TNF-α, IL-6, IL-10, and IFN-γ in the lung." (PMID 37174654, 2023). "Overproduction of inflammatory mediators and cytokines, such as inflammasome complexes, IL‐6, IL‐1β, and TNF‐α, can also lead to lung fibrosis in affected patients." (PMID 37773712, 2023). "What is the anti-pulmonary fibrosis molecular target in NF-κB/TNF-α pathway for the active components of FZHY?" (PMID 35548340, 2022). "The double staining result showed that macrophage is the main resource of TNF-α and increased in bleomycin-induced pulmonary fibrosis in mice." (PMID 35548340, 2022). "In this study, hMIKO-1 administration suppressed pulmonary fibrosis and the expression of F4/80, inflammatory cytokines (TNF-α, IL-6, and IL-1β), and fibrotic factors in the lungs of BLM-ILD mice." (PMID 36077067, 2022). "For the TNF-Tg model used in this study, It has been previously reported that TNF-Tg mice have lung lesions, including pulmonary inflammatory cell accumulation, pulmonary arteriole thickening, pulmonary fibrosis, and emphysema." (PMID 35600883, 2022). "Based on the analysis results of network pharmacology, we further verified the anti-pulmonary fibrosis mechanism of FZHY by inhibiting TNF pathway in vivo and in vitro." (PMID 35548340, 2022). "It has also been demonstrated that the pro-inflammatory cytokine TNF-α induces NF-κB activation, promoting myofibroblast differentiation of the lung resident mesenchymal stem cells, and exacerbates bleomycin-induced pulmonary fibrosis." (PMID 36353104, 2022). "The results revealed that TNF signaling pathway was markedly ranked first for FZHY action mechanism against lung fibrosis." (PMID 35548340, 2022). "Their vivo study demonstrated that pre-treatment with GW4869 decreased lung fibrosis and the expression of TNF-α, IL-1β, and IL-6 in silicosis model." (PMID 35677105, 2022). "Research using an animal model of pulmonary fibrosis also revealed that elevated synthesis and release of TNF stimulated the proliferation of fibroblasts and promoted collagen synthesis, events that caused pulmonary fibrosis." (PMID 35360660, 2022).
pulmonary fibrosis (continued). "TNF-α is a proinflammatory cytokine that has been extensively reported to be an important factor in the pathogenesis of pulmonary fibrosis." (PMID 36421687, 2022). "Bronchoalveolar lavage fluid showed reduced pulmonary fibrosis and expression of tumor necrosis factor (TNF)-α, interleukin (IL)-1β, and IL-6 after treatment with EVs inhibitors." (PMID 36032078, 2022). "Higher levels of TNF-α were also discovered in mice with early pulmonary fibrosis, which is consistent with the results of this study." (PMID 35889786, 2022). "Richard D Bell found that in addition to RA symptoms, TNF-Tg mice are also complicated by pulmonary interstitial fibrosis and right ventricular hypertrophy." (PMID 35600883, 2022). "Although fibroblasts activation and differentiation played a pivot role in lung fibrogenesis, inflammatory mediators such as TNF and IL-1β have an important effect on the initiation and development of lung fibrosis." (PMID 35548340, 2022). "In this study, we also found that TNF-Tg mice had pulmonary inflammatory cell aggregation and pulmonary fibrosis, as well as obvious thickening of the alveolar septum." (PMID 35600883, 2022). "Studies have shown that TNF was a prerequisite for the development of pulmonary fibrosis, and TNF−/− mice were completely unaffected by inflammation and fibrosis." (PMID 35548340, 2022). "The release of proinflammatory cytokines like TNF-α, IL-1β, and IL-6 in the lung tissue microenvironment by stimulated macrophages and fibroblasts contributes to the persistence of lung fibrosis by activating fibroblasts in an autocrine/paracrine fashion." (PMID 35377906, 2022). "TGFß has been shown to induce full EndoMT in cultured endothelial cells from different tissues, whereas serum levels of TNFα are elevated in patients with SSc and favor the development of pulmonary fibrosis and pulmonary arterial hypertension." (PMID 36209279, 2022). "Overall, our findings suggest PL as an anti-fibrotic agent acting via down-regulation of TGF-β/CTGF or ET-1 axis, as well as TNF-α, to improve lung fibrosis." (PMID 36271442, 2022). "Levels of cytokines, such as tumor necrosis factor-alpha (TNF-α) and interleukin-6, are increased with IR and cause lung fibrosis and inflammation." (PMID 33794844, 2021). "Liposomal quercetin was demonstrated to attenuate bleomycin-induced pulmonary fibrosis in vivo by the suppression of inflammatory cytokines (TNF-α, IL-1β, and IL-6) and the diminish of total cells and macrophage counts in BALF." (PMID 35126133, 2021). "This anti-inflammatory effect of piperine through TNF-α reduction has been previously proved in microcystin-induced hepatotoxicity, bleomycin-induced pulmonary fibrosis, isoprenaline-induced myocarditis, and chronic pancreatitis." (PMID 34778375, 2021). "More importantly, an in vivo study demonstrated that pre‐treatment with GW4869 decreased lung fibrosis and the expression of TNF‐α, IL‐1β and IL‐6 in BALF." (PMID 33834616, 2021). "Previous studies have shown that TNFα accelerates lung fibrosis resolution in mice in a bleomycin injury model." (PMID 33688918, 2021). "After adjustment for age, the PMN %, TNF-α, IL-1B, SDF-1α, MMP1, and calprotectin were associated with lung fibrosis (kurtosis and skewness) and density (HAA)." (PMID 34682263, 2021). "Experimental animal models show that TNF-α over expression induces the pathological changes similar to emphysema and pulmonary fibrosis." (PMID 33915841, 2021). "Increased production of TNFα, together with IL1ꞵ from the macrophages, have been reported in pulmonary fibrosis." (PMID 34960806, 2021). "IPF outcomes are worsened by treatment with low dose Prednisone, Azathioprine, and unaffected by treatment with biologics targeting interferon gamma or TNFα." (PMID 34434962, 2021). "Various growth factors and cytokines are involved in pulmonary fibrosis, including tumor necrosis factor alpha (TNF-α) and TGF-β." (PMID 34082837, 2021).
pulmonary fibrosis (continued). "Various investigations have revealed that Thal prevents bleomycin- or paraquat-induced pulmonary fibrosis in murine models by downregulating the expression of IL-6, IL-8, IL-1β, TNF- α, TGF-β, collagen, hydroxyproline, VEGF, p-JNK and α-SMA." (PMID 35126133, 2021). "Together with interleukins and TNFα genes, novel cannabis extracts regulated the expression of various other genes involved in fibrosis, including pulmonary fibrosis (PF)." (PMID 33465050, 2021). "It is also observed that TNF-α induced ROS and intracellular glutathione depletion in the airway epithelial cells induces the production of AP-1 and leads to the pulmonary fibrosis." (PMID 33841751, 2021). "The signaling of TNF-α through its receptors seems to be essential in pulmonary fibrosis development." (PMID 35082682, 2021). "The effects include reduced in the levels of inflammatory mediators such as IL-6 and TNF-α, improved pulmonary angiogenesis, ameliorated lung fibrosis and restored alveolar structures in BPD experimental models." (PMID 33791258, 2021). "MLN4924 inhibits the production of cytokines, including TNF-α, and its efficacy in bleomycin-induced idiopathic pulmonary fibrosis models has been shown." (PMID 33560503, 2021). "In accord, a soluble receptor for TNF-α was shown to alleviate bleomycin-induced pulmonary fibrosis." (PMID 35082682, 2021). "Some studies have also shown that over-expression of either TNFα or IL-1β in mouse lungs leads to spontaneous pulmonary fibrosis." (PMID 33999928, 2021). "And sodium houttuyfonate inhibited the expression of inflammatory cytokine TNF-α, which was consistent with our previous findings in bleomycin-induced pulmonary fibrosis in mice." (PMID 34658873, 2021). "Administration of recombinant human TNF-α also attenuates bleomycin-induced pulmonary fibrosis in mice." (PMID 35082682, 2021). "Another study showed that 100 mg/kg of saffron reduced MDA, Myeloperoxidase, and tumor-necrosis factor-alpha (TNF-α) in pulmonary fibrosis." (PMID 34195027, 2021). "TNF-α aggravates inflammation and promotes pulmonary fibrosis through NF-κB pathway and by upregulating expression of TGF-β, platelet-derived growth factor (PDGF)-α and PDGF-β." (PMID 34876129, 2021). "The inflammatory molecule tumor necrosis factor α (TNFα) has been shown to activate latent TGFβ while overexpression of interleukin 1β (IL-1β) sustains TGFβ expression and promotes lung fibrosis." (PMID 34011367, 2021). "Improved lung function and reduced alveolar collapse.Reduced lung inflammation and lung fibrosis.Reduced TNF-α, IL-1β, KC, and TGF-β levels.Reduced apoptosis in the lung, kidney, and liver." (PMID 32519302, 2020). "Previous studies have demonstrated that YY1 is up-regulated in lung fibroblasts induced by transforming growth factor-β (TGF-β) or tumor necrosis factor-α (TNF-α), both of which are central pro-fibrotic mediators of pulmonary fibrosis." (PMID 32396525, 2020). "The release of tumor necrosis factor (TNF) caused by Mycobacterium tuberculosis infection leads to pulmonary inflammation, and pulmonary fibrosis induced by M. tuberculosis results in synthesis of extracellular matrix (ECM) components." (PMID 33537234, 2020). "Our analysis showed that eight genes (CSF2, CSF3, CXCL2, CXCL8, IL1B, IL6, MMP9, and TNF) are significantly overlapping with the lung fibrosis pathway with p-value 9.35e-11." (PMID 33362771, 2020). "Activation of p38 MAPK signaling pathway in pulmonary macrophages promotes lung fibrosis through secretion of IL-6, IL-1β, and TNF-α, all of which are the direct targets of p38 MAPK pathway." (PMID 32271749, 2020). "TGF-β1 and TNF-α upregulation is believed to play important role in the development of pulmonary fibrosis." (PMID 33066398, 2020). "For example, lung fibrosis-associated genes (CSF3, IL8, CSF2, IL6, TNF, MMP9, IL1B and PDGFB) were significantly upregulated in SARS-CoV-2-infected NHBE cells." (PMID 32698440, 2020).